CRP (C-reactive protein)
Diseases named in the same sentence as CRP in open-access papers (continued):
Sharing a sentence is not in itself a finding about the gene and the disease.
lymphopenia (continued). "In adults, biochemical markers associated with a severe form of disease are: lymphopenia, neutropenia, elevated serum ALT, AST, LDH, CRP, and ferritin." (PMID 35626368, 2022). "The presence of lymphopenia, high CRP, D‐dimer, and ferritin values, which are employed to predict the severity of the disease in Covid pneumonia, are the standard prognostic parameters in this respect." (PMID 35750636, 2022). "Laboratory data showed elevated inflammatory markers (C-reactive protein, fibrinogen, ferritin, D-dimer), neutrophilia with lymphopenia, normal platelet counts and hemoglobin levels, and increased cardiac biomarkers in both groups." (PMID 36034550, 2022). "In these cases, there were factors described as well as lymphopenia or plaquetopenia, high levels of troponin, ferritin, C-reactive protein, brain natriuretic peptide, and N-terminal pro BNP type B, D-dimer or interleukin-6." (PMID 36498573, 2022). "The disease exhibits symptoms like severe pneumonia, associated to a severe inflammatory reaction including high C-reactive protein (CRP) and interleukin-6 (IL-6) levels, low albumin and eosinophils, but high sedimentation rate and lymphopenia." (PMID 36211365, 2022). "Lymphocytopenia (59%) with elevated C-reactive protein (70%) was also observed, and 91% of the women delivered by cesarean section." (PMID 35044301, 2022). "First, we reanalyzed the incidence of lymphopenia, and the elevation of CRP, fibrinogen, and D-dimer in these two groups using Fisher’s exact test." (PMID 35304437, 2022). "The same study showed that lymphopenia, thrombocytopenia, elevated D-dimer, elevated CRP, then elevated CK, AST, ALT, LDH, and creatinine are independent predictors of deadly disease outcomes." (PMID 35237386, 2022). "A percentage of patients had leucopenia (7/70, 10.0%) or lymphopenia (24/70, 34.3%) on admission, and elevated C-reactive protein was observed in 40.3% of patients." (PMID 35646992, 2022). "When he was 16 months old, laboratory evaluation revealed lymphopenia, neutropenia, thrombocytosis, and increased levels of C-reactive protein (CRP)." (PMID 36566211, 2022). "Laboratory examination revealed leukopenia, lymphopenia, and a significant increase in C-reactive protein (CRP), and the patient underwent oxygen supplementation therapy." (PMID 36310874, 2022). "While lymphopenia and thrombocytopenia are seen in the early phase, C-reactive protein (CRP), aspartate aminotransferase (AST), and alanine aminotransferase (ALT) increases are observed in the pulmonary phase." (PMID 36168388, 2022). "Patients with high concentration of NT-proBNP, troponin, CRP, lactates, ferritin, D-dimers, and creatinine and a lower concentration of PLT, albumin, leukocytes, lymphopenia, and hyponatremia are at risk for immunoglobulin treatment resistance." (PMID 35948653, 2022). "C-reactive protein levels greater than the median value, neutrophilia, lymphopenia, and neutrophil-to-lymphocyte ratio were significantly associated with higher mortality." (PMID 35188551, 2022). "MIS-C also has higher inflammatory markers (CRP, ferritin, and D-dimer) and more lymphopenia and thrombocytopenia." (PMID 34991644, 2022). "The women who required admission to ICU and oxygen therapy, or mechanical ventilation, presented with leukopenia and lymphopenia, elevated levels of CRP, D-dimer, lactate dehydrogenase (LDH) and interleukin 6 (IL-6)." (PMID 36430023, 2022). "There was a higher neutrophilia (p = 0.01), D-dimer (p = 0.02), lymphopenia (p = 0.14), and raised CRP (p = 0.002) in obstetric cohort." (PMID 35602816, 2022). "Patients with severe pneumonia had more prominent laboratory abnormalities, including lymphopenia, elevated C-reactive protein levels, and elevated lactate dehydrogenase levels than non-severe cases (all P < 0.05)." (PMID 35646992, 2022).
lymphopenia (continued). "Patients with high PSMA4 and PSMA5 mRNA expression suggested more acute lymphopenia, more severe hypoxemia and higher concentrations of C-reactive protein and ferritin in plasma." (PMID 35327634, 2022). "The most common laboratory findings in the affected women were increased CRP, lymphopenia, decreased white blood cells, and increased liver enzymes." (PMID 36187739, 2022). "The main laboratory findings found in our study were lymphopenia (18.8%) and elevated CRP (71.88%), D-dimer (91.67%), ALT (6.2%), and AST (6.25%) levels." (PMID 35592844, 2022). "Patients from rural areas were also more likely to enter the hospital with laboratory evidence indicating hyperinflammation, such as elevated C-reactive protein and lymphopenia, compared to patients from urban areas." (PMID 35976813, 2022). "The most common laboratory abnormalities noted were elevated N-terminal-pro B-type natriuretic peptide, CRP, D-dimer, ferritin, fibrinogen, and procalcitonin; and lymphopenia and thrombocytopenia." (PMID 35172274, 2022). "In a meta-analysis of 176 SARS-CoV-2-positive neonates, 97 had clinical symptoms related to SARS-CoV-2 infection, 14.4% had lymphopenia, 15.5% had elevated inflammatory markers (e.g., CRP and procalcitonin), and 4% had elevated liver enzymes." (PMID 35530886, 2022). "In that study, lymphopenia high lactate dehydrogenase levels, hemoglobin, hematocrit, ferritin, aspartate aminotransferase, alanine aminotransferase, CRP, and PCT were observed more frequently in male patients." (PMID 35979974, 2022). "In another study, lymphocytopenia, leukopenia, increased CRP, and lactic dehydrogenase were reported in 64.5%, 29.4%, 44.3%, and 28.3% of cases, respectively." (PMID 35872680, 2022). "As expected, laboratory testing showed elevated inflammatory markers (C-reactive protein, fibrinogen, ferritin, D-dimer), neutrophilia with lymphopenia, and increased cardiac biomarkers." (PMID 35135600, 2022). "The most common laboratory findings in the women were: increased C-reactive protein (67.90%), lymphopenia (18.51%), decreased white blood cells (27.16%), and increased liver enzymes (18.51%)." (PMID 36187739, 2022). "The results of his laboratory tests showed a lymphopenia (lymph count: 912), CRP: 12 mg/L, IL‐6: 294, and LDH: 1117 U/L." (PMID 35169468, 2022). "Laboratory testing showed elevated inflammatory markers (C-reactive protein, fibrinogen, ferritin, D-dimer levels), neutrophilia with lymphopenia, and increased cardiac biomarkers." (PMID 36034550, 2022). "Lymphopenia, tachycardia, tachypnea, elevated CRP, d‐dimer, serum ferritin, LDH, and decreased SpO2 were significantly associated with complicated cases (p < .05 for all)." (PMID 35894709, 2022). "Elevated CRP, NLR, lymphopenia and neutrophilia are linked to systemic infections and the development of pneumonia, all common outcomes from infection with SARS‐Cov2." (PMID 35941886, 2022). "Most patients became infected after direct contact with a positive patient (N = 111, 68.5%) and the most common symptoms (cough, fever, malaise) and laboratory abnormalities (lymphopenia, elevated C-reactive protein) were in line with what was expected." (PMID 35770002, 2022). "Differences in laboratory parameters were seen in lymphopenia (p<0.001) with significantly higher levels of lactate, base deficit, CRP, aspartate aminotransferase (AST), urea, creatinine, and D-dimer levels seen in patients who died." (PMID 35464509, 2022). "SARS-CoV-2 patients showed lymphopenia, along with increased inflammation markers including ferritin, CRP and IL-6 levels." (PMID 35126186, 2021). "Increased levels of the inflammatory and coagulation markers CRP, ferritin, and D-dimer and lymphopenia were commonly observed at diagnosis and were more marked before death." (PMID 34440207, 2021).
lymphopenia (continued). "The decreased amount of lymphocyte (lymphopenia) and neutrophil (neutrophilia), together with the increased number of CRP and LDH, showed the immunological response to the virus, followed by severe virus infection." (PMID 34541519, 2021). "Laboratory results revealed elevated acute phase reactants (C-Reactive protein (CRP) 5.9 mg/dl, ferritin 1269 ng/ml, D-dimer 18547 ng/ml, lactate dehydrogenase 781 U/L and lymphopenia (4%))." (PMID 33761696, 2021). "In COVID‐19 cohort, we found a lymphopenia in 58.9% of cases, elevated values of CRP, a rise of d‐dimer and of LDH." (PMID 33960733, 2021). "Lactate was 2.2 mmol/L, capillary glucose 4.4 mmol/L and capillary ketones 5.2 mmol/L: CRP was 49 mg/L with a lymphopenia of 0.7 × 109/L." (PMID 34134652, 2021). "At baseline, severe lymphopenia, leukopenia, elevated levels of CRP, D-Dimer, lipase, and amylase were present in both groups, clinical features already observed in other studies." (PMID 33815368, 2021). "With time progression, peripheral blood results reflect worsening lymphopenia, more significant elevations in CRP and LDH as well as that for neutrophil counts." (PMID 33482780, 2021). "Variables that remained independently associated with death in men included age >70 years, public insurance, incremental increase in qSOFA, and CRP, lymphocytopenia, and thrombocytopenia." (PMID 36168478, 2021). "We also observed raised MCHC, a reduction in eosinophils, low albumin levels, high CRP, and lymphopenia." (PMID 34031483, 2021). "Severe and critical patients show lymphopenia or increased levels of serum C-reactive protein (CRP), hypoalbuminemia, alanine aminotransferase, lactate dehydrogenase, ferritin, and/or D-dimer." (PMID 34721388, 2021). "In contrast to Western literature, our cancer patients demonstrated significant lymphopenia and elevated inflammatory markers (CRP and IL‐6) versus non‐cancer patients." (PMID 34786866, 2021). "Blood analysis revealed an increased CRP level (35.6 mg/L, normal value < 5.0 mg/L), lymphopenia (0.3 × 109/L, normal range 1.2–3.6 × 109/L), and neutropenia (1.6 × 109/L, normal range 2.5–7.8 × 109/L)." (PMID 33670394, 2021). "In our study, lymphopenia was detected in 20.7% of the cases, thrombocytopenia in 4.2%, high CRP in 32.6%, LDH in 54.3%, D-Dimer in 26.3% and Ferritin in 31.3%." (PMID 34803451, 2021). "On admission, all patients presented with a biological inflammatory syndrome with high C-reactive protein (mean 197.3mmol/L ± 86.4) level and lymphopenia (0.7g/L ± 0.33), defined as a lymphocyte count lower than 1,500g/L." (PMID 33886855, 2021). "In their model high lactate dehydrogenase (LDH), low lymphocyte count (lymphopenia) and high levels of high sensitivity C-reactive protein (hs-CRP) were found to be predictors of mortality." (PMID 33793600, 2021). "Systemic lupus erythematosus (SLE), for example, is characterized by expansion of plasmablast numbers in proportion to autoantibody repertoire, while in contrast, AAV is characterized by naïve lymphopenia in proportion to CRP." (PMID 35095887, 2021). "In our analysis, the PANDEMYC score is able to identify a population with a higher prevalence of comorbidities and pro-inflammatory status inferred through a significant increase in concentrations of CPK, LDH, CRP, or lymphopenia." (PMID 34884180, 2021). "Their comparison with MIS-C group showed lymphopenia, thrombocytosis, and higher CRP as well as more frequent atypical presentation in MIS-C KD group with less coronary involvement." (PMID 34153080, 2021). "Older age, comorbid conditions, elevated body mass index, lymphopenia, and elevated levels of C reactive protein (CRP), lactate dehydrogenase (LDH), d-dimer, ferritin, and sIL-2r have been associated with intensive care unit (ICU) admission and death." (PMID 33803997, 2021).
lymphopenia (continued). "Laboratory tests showed the white blood cell count at 10 900/mm3, lymphopenia at 800/mm3, 0 eosinophils per mm3, mildly increased liver enzymes, elevated C-reactive protein (CRP) concentration and procalcitonin at 208 mg/l and 2.41 ng/ml, respectively." (PMID 32907688, 2021). "Due to the importance of early diagnosis of this disease, a series of biochemical parameters have been identified as possible biomarkers of its severity, including lymphopenia and increased D-dimer levels ferritin troponin and C-reactive protein (CRP)." (PMID 34071293, 2021). "We show that few had the classical finding of lymphopenia, and relatively mild increases in c-reactive protein." (PMID 34646345, 2021). "Further evaluation revealed lymphopenia, thrombocytopenia, and elevated levels of C-reactive protein (CRP), ferritin, and fibrinogen." (PMID 34961833, 2021). "Blood tests documented lymphopenia (white blood cells 6,180/μl, lymphocytes 660/μl); an increase in inflammatory indices (CRP 70.4 mg/l, PCT 1 ng/ml), D-dimer (1.25 mg/l), and fibrinogen (550 mg/dl); and a mild hyponatremia (134 mmol/l)." (PMID 34422717, 2021). "Of the 18 patients presenting to hospital, 16 (88.9%) most commonly had an elevated lactate dehydrogenase level, liver function derangement, an elevated C-reactive protein level, or lymphopenia on blood tests." (PMID 33529157, 2021). "In the results of laboratory tests, the typical symptoms were leukopenia and lymphopenia (approximately 17% and 13%, respectively) and elevated CRP levels, which is consistent with our observations." (PMID 33802763, 2021). "No relevant alterations were found in parameters from ASY that are usually observed in SY, such as lymphopenia and thrombocytopenia, along with high levels of CRP and bilirubin and lower levels of cholesterol." (PMID 34714821, 2021). "Neutrophils and C-reactive protein (CRP) levels were observed to be raised in all patients, while lymphopenia was observed in 114/120, and D-dimer levels were elevated in 102 (85%) patients." (PMID 35004038, 2021). "The most laboratory abnormalities found in patients were lymphopenia, increased levels of C-reactive protein/erythrocyte sedimentation rate (CRP/ESR), increased lactate dehydrogenase (LDH) level, high IL-6 level, high ferritin and increased d-dimer level." (PMID 34952570, 2021). "Laboratory findings included lymphopenia and thrombocytopenia in most patients, as well as evidence of coagulopathy and elevated inflammatory markers such as C-reactive protein, ferritin and procalcitonin." (PMID 34103044, 2021). "She tested positive for SARS-CoV-2 and the results of her laboratory investigations showed lymphopenia, thrombocytopenia, and elevated CRP." (PMID 33803475, 2021). "Profound lymphopenia, high CRP, high clinical frailty score and cumulative morbidity were associated with a higher chance of mortality." (PMID 33043852, 2021). "Most common laboratory findings include lymphopenia and thrombocytopenia and elevated CRP, ferritin, PCT, D-dimers, PT, NT-proBNP and troponin." (PMID 34103044, 2021). "The most common laboratory abnormalities include an increased C-reactive protein level (68.6%), lymphopenia (57.4%), and an increased lactate dehydrogenase level (51.6%)." (PMID 33529157, 2021). "Subsequent laboratory tests revealed worsening lymphopenia, raised CRP (median 159 mg/L, IQR 81–299) and intracellular enzymes, and impaired hepatic, renal, and haemostatic function." (PMID 33564474, 2021). "Laboratory evaluation revealed neutrophilia and lymphopenia along with elevated C-reactive protein, erythrocyte sedimentation rate, troponin, lactate dehydrogenase, ferritin, and D-dimer." (PMID 34642609, 2021). "The most common abnormalities included increased levels of C-reactive protein, D-dimer, and lymphopenia." (PMID 33802763, 2021).
lymphopenia (continued). "Our findings were significant, including neutrophilia, lymphopenia, elevated D-dimer levels, increased CRP, AST, serum ferritin, creatinine, BUN, and decreased serum total protein." (PMID 33884042, 2021). "The pooled proportion of patients with lymphocytopenia (<1000 cells/mm3) and high CRP (>5 mg/dL) was 79% (95% CI, 70–89%) and 60% (95% CI, 35–84%), respectively." (PMID 34640552, 2021). "It should be noted that, similarly, numerous other biochemical markers have been described to identify the most severe patients, including lymphopenia, neutrophils, neutrophil to lymphocyte ratio, CRP level, and D-Dimers." (PMID 33567583, 2021). "In terms of contribution to the separation of severe/critical from mild/moderate cases, the loadings for PC1 illustrated that the significance rank was CRP > D‐dimer > LDH > prealbumin > lymphopenia." (PMID 33112011, 2021). "Almost all patients had elevated CRP levels, and more than half had ferritin levels above 500 mg/dL, d-dimer levels >1 ng/mL, and lymphocytopenia." (PMID 34664862, 2021). "In 22 patients, results from laboratory studies included raised values of CRP (73%), ferritin (59%), D-dimer (52%) and liver enzymes (48%) and lymphopenia (52%) as the most frequent abnormalities." (PMID 34071924, 2021). "Clinical follow-up revealed thrombocytopenia, lymphopenia and increased polyclonal immunoglobulins and C-reactive protein." (PMID 33472608, 2021). "The capillary glucose measured 4.2 mmol/L and capillary ketones 6.8 mmol/L: CRP measured 102 mg/L, and a lymphopenia of 0.6 × 109/L." (PMID 34134652, 2021). "Levels of C-reactive protein were higher and lymphopenia more distinctive, indicating a more severe disease course." (PMID 34202697, 2021). "An association, through univariate analysis, with COVID‐19 diagnosis has been reported for lymphopenia, CRP elevation, high levels of LDH and AST." (PMID 33960733, 2021). "It is a cytokine storm syndrome induced by SARS-CoV-2 with very high inflammation markers: C-reactive protein, pro-calcitonin, pro-inflammatory cytokine levels, mainly IL-6 and IL-10, soluble IL-2 receptor, ferritin, D-dimers lymphopenia and neutrophilia." (PMID 34359355, 2021). "Blood tests showed normal white blood cell count (7,760/μl) with lymphopenia (L: 710/μl) and increased inflammatory markers (C-reactive protein CRP: 89.7 mg/l, normal range: 0–5; procalcitonin PCT: 8.9 ng/ml, normal range: 0.02–0.5)." (PMID 34422717, 2021). "Laboratory results showed lymphopenia (normal value 1.5–4 × 109/L) in 203 patients (22.5%), elevated CRP (50 mg/L) in 236 patients (40.3%), high d-dimer (>1 mcg/mL) in 147 (16.2%), and elevated ferritin level (>600 ng/mL) in 301 (33.3%)." (PMID 33505722, 2021). "In patients with available laboratory values, 69% had CRP levels above 120 mg/L, while leukopenia was found in one-fifth (21%) and lymphopenia and neutropenia in 89% and 20%, respectively." (PMID 33159569, 2021). "The patients with severity of disease progression presented at admission with neutrophilia, lymphopenia and higher levels of D-dimer, ferritin, C-reactive protein, procalcitonin and fibrinogen." (PMID 33882060, 2021). "Lymphopenia was a common tract shared by 58.9% of cases, as well as the elevated values of CRP (88.8%), the rise of d‐dimer (76.7%) and of LDH (64.5%)." (PMID 33960733, 2021). "Another study suggested that patients need critical care if they have high D-dimer and CRP levels or thrombocytopenia and lymphopenia." (PMID 34650947, 2021). "In laboratory parameters, raised C reactive protein (CRP) levels (49% of patients), lymphopenia (33%), and increased leukocyte count (in 26% of patients) were the most common findings." (PMID 34830740, 2021). "By comparing the peripheral blood investigation findings between the earlier phase (DOO ≤ 7 days) and the later phase (DOO > 7 days) of the disease, there was more prominent lymphopenia and raised inflammatory markers like CRP and LDH levels in the latter." (PMID 33482780, 2021).